RN7SL205P (RNA, 7SL, cytoplasmic 205, pseudogene)
Gene: Miscellaneous RNA gene on chromosome 4 (131,720,260 to 131,720,543, reverse strand). Ensembl gene ENSG00000241392.
Homologues: Orthologues: chimpanzee Metazoa_SRP (98% identical), macaque Metazoa_SRP (94% identical). Paralogues in human: RN7SL565P (97% identical), RN7SL722P (97% identical), RN7SL787P (97% identical), RN7SL52P (97% identical), RN7SL544P (97% identical), RN7SL763P (97% identical), RN7SL1 (81% identical), RN7SL2 (81% identical), RN7SL3 (81% identical), RN7SL230P (80% identical), RN7SL322P (80% identical), RN7SL709P (80% identical), and 704 more.